Y_RNA (Y RNA )
Gene: Miscellaneous RNA gene on chromosome 2 (120,192,245 to 120,192,357, forward strand). Ensembl gene ENSG00000202046.
Homologues: Orthologues: chimpanzee Y_RNA (99% identical), macaque Y_RNA (94% identical). Paralogues in human: RNY1 (88% identical), Y_RNA (86% identical), Y_RNA (85% identical), Y_RNA (84% identical), Y_RNA (83% identical), Y_RNA (82% identical), Y_RNA (81% identical), RNY1P11 (80% identical), RNY1P8 (80% identical), Y_RNA (80% identical), RNY1P7 (79% identical), Y_RNA (79% identical), and 96 more.